TPCN1 (two pore segment channel 1)
Description:
Intracellular channel initially characterized as a non-selective Ca(2+)-permeable channel activated by NAADP (nicotinic acid adenine dinucleotide phosphate), it is also a voltage-gated highly-selective Na(+) channel activated directly by PI(3,5)P2 (phosphatidylinositol 3,5-bisphosphate) that senses pH changes and confers electrical excitability to organelles. Localizes to the early and recycling endosomes membranes where it plays a role in the uptake and processing of proteins and regulates organellar membrane excitability, membrane trafficking and pH homeostasis (Probable). Ion selectivity is not fixed but rather agonist-dependent and under defined ionic conditions, can be readily activated by both NAADP and PI(3,5)P2 (Probable). Required for mTOR-dependent nutrient sensing (Probable). (Microbial infection) During Ebola virus (EBOV) infection, controls the movement of endosomes containing virus particles and is required by EBOV to escape from the endosomal network into the cell cytoplasm.
Synonyms: KIAA1169; TPC1; FLJ20612
Tractability: Small molecule: it belongs to a druggable protein family. Antibody: UniProt places it where antibodies can reach, with high confidence; UniProt predicts a signal peptide or a membrane-spanning region. PROTAC: ubiquitination databases record sites on it; its protein half-life has been measured.
Gene: Protein-coding gene on chromosome 12 (113,221,050 to 113,298,589, forward strand). Ensembl gene ENSG00000186815.
Subcellular location: Lysosome membrane; Endosome membrane; Early endosome membrane; Recycling endosome membrane
Pathways (Reactome):
Transport of small molecules: Stimuli-sensing channels
Gene Ontology:
Molecular function: identical protein binding; intracellularly phosphatidylinositol-3,5-bisphosphate-gated monatomic cation channel activity; ligand-gated sodium channel activity; NAADP-sensitive calcium-release channel activity; protein binding; voltage-gated sodium channel activity; monoatomic ion channel activity; phosphatidylinositol-3,5-bisphosphate binding; protein homodimerization activity; voltage-gated channel activity
Biological process: endocytosis involved in viral entry into host cell; positive regulation of autophagy; monoatomic ion transmembrane transport; calcium-mediated signaling; monoatomic ion transport; sodium ion transmembrane transport; transmembrane transport
Cellular component: endolysosome; endosome membrane; lysosomal membrane; early endosome membrane; endosome; lysosome; recycling endosome membrane; membrane
Genetic constraint (gnomAD): Loss-of-function variants: 48 observed, 105.29 expected, observed/expected ratio (o/e) 0.46, 90% interval 0.36 to 0.58. The upper end of that interval is the gene's LOEUF score, 0.58, which puts it in group 2 of 6, group 1 being the genes least tolerant of losing a copy. Missense variants: 779 observed, 1,075.2 expected, observed/expected ratio (o/e) 0.72, 90% interval 0.68 to 0.77. Synonymous variants: 437 observed, 441.98 expected, observed/expected ratio (o/e) 0.99, 90% interval 0.91 to 1.07.
Homologues: Orthologues: chimpanzee TPCN1 (99% identical), macaque TPCN1 (99% identical), pig TPCN1 (94% identical), dog TPCN1 (94% identical), guinea pig TPCN1 (92% identical), mouse Tpcn1 (91% identical), rat Tpcn1 (90% identical), rabbit TPCN1 (89% identical), zebrafish tpcn1 (70% identical), tropical clawed frog TPCN1 (63% identical). Paralogues in human: SCN3A (21% identical), CACNA1E (21% identical), SCN2A (21% identical), CACNA1A (21% identical), SCN8A (21% identical), SCN4A (20% identical), SCN1A (20% identical), SCN5A (20% identical), CACNA1B (20% identical), SCN9A (20% identical), CACNA1D (20% identical), CACNA1C (19% identical), and 14 more.
Diseases named in the same sentence as TPCN1 in open-access papers:
TPCN1 is named in the same sentence as 27 diseases in open-access papers, as found by Europe PMC text mining. Sharing a sentence is not in itself a finding about the gene and the disease. The quoted sentences say what the papers report.
Obesity (3 papers, 2016 to 2025). Accumulation of substantial excess body fat. "TPCN1/2(-/-) mice show mature-onset obesity due to reduced lipid availability and use, as well as a defect in β-adrenergic receptor signaling, leading to impaired thermogenic activity in brown adipose tissue." (PMID 26918892, 2016). "For instance, a study conducted on male mice found that knockout of TPCN1 and TPCN2 leads to obesity in adulthood due to impaired lipid availability for thermogenesis in brown adipose tissue." (PMID 41465472, 2025).
allergic disease (2 papers, 2023). An immune response that occurs following re-exposure to an innocuous antigen, and that requires the presence of existing antibodies against that antigen. "When exploring the biological impact of other genes mapped to the dmCpGs uniquely associated with father’s pubertal smoking, several were related to genes associated with innate immunity, allergic diseases and asthma development, such as TLR9, CSF1R, DNAJ14, NTRK2 and TPCN1." (PMID 37649101, 2023). "Some calcium signaling pathway-related genes, such as ERBB2, PDE1B, PDGFA, TPCN1, and MCU, have been reported to participate in the development of allergic diseases." (PMID 37328853, 2023).
cardiac hypertrophy (2 papers, 2012 to 2025). "Up-regulated genes bound by TWIST1 included the two pore channel Tpcn1; the Rho activating protein, Abra, which has been implicated in cardiac hypertrophy; the kinase Sik1; and the uncharacterized genes Gatsl2 and Wdr75." (PMID 22815831, 2012).
asthma (1 paper, 2023). "Some of these sites were associated with offspring outcomes in this cohort including ever-asthma (NTRK2), ever-wheezing (DNAJC14, TPCN1), weight (FAM53B, NTRK2) and BMI (FAM53B, NTRK2) (p < 0.05)." (PMID 37649101, 2023).
dilated cardiomyopathy (1 paper, 2020). Cardiomyopathy which is characterized by dilation and contractile dysfunction of the left and right ventricles. "A TPCN1 missense variant p.(Arg199Gln) had occurred de novo in a patient with early-onset, devastating dilated cardiomyopathy." (PMID 32037394, 2020).
lysosomal storage disorder (1 paper, 2024). "Perinuclear lysosome redistribution was seen in cells overexpressing TRPML1-L106P (a mutant associated with mucolipidosis type IV, an autosomal recessive lysosomal storage disorder), TPCN1, and TPCN2, but not with wild-type TRPML1, when treated with P4." (PMID 38295116, 2024).
pulmonary stenosis (1 paper, 2020). "We also report novel plausible gene–disease associations for tetralogy of Fallot/pulmonary stenosis (CDC42BPA, FGD5), hypoplastic left or right heart (SMARCC1, TLN2, TRPM4, VASP), congenitally corrected transposition of the great arteries (UBXN10), and early-onset cardiomyopathy (TPCN1)." (PMID 32037394, 2020).
viral infection (1 paper, 2024). "TPCN1 is very important in regulating calcium ion homeostasis and lysosomal function, and has been linked to various physiological processes such as autophagy, apoptosis, and viral infection." (PMID 38347953, 2024).
TPCN1 also shares sentences with these, for which no sentence is quoted: infection (4 papers); breast carcinoma (2); cancer (2); metastatic colorectal cancer (2); anaphylaxis (1); COVID-19 (1); diabetes (1); Ebola (1); heart failure (1); influenza infection (1); melanoma (1); microcephaly (1); mucolipidosis type IV (1); myocardial infarction (1); neurodevelopmental disorder (1); Parkinson disease (1); pulmonary artery hypertension (1); Tetralogy of Fallot (1); unipolar depression (1).